FGL2 (fibrinogen like 2)
Description:
May play a role in physiologic lymphocyte functions at mucosal sites.
Synonyms: pT49; T49
Tractability: Antibody: its Gene Ontology location is reachable by antibodies, with high confidence; UniProt places it where antibodies can reach, with medium confidence; UniProt predicts a signal peptide or a membrane-spanning region. PROTAC: its protein half-life has been measured.
Gene: Protein-coding gene on chromosome 7 (77,193,369 to 77,199,848, reverse strand). Ensembl gene ENSG00000127951.
Subcellular location: Secreted
Pathways (Reactome):
Immune System: Neutrophil degranulation
Gene Ontology:
Molecular function: protein binding; extracellular matrix structural constituent
Cellular component: extracellular exosome; extracellular matrix; extracellular region; fibrinogen complex; ficolin-1-rich granule lumen; non-collagenous component of interstitial matrix
Genetic constraint (gnomAD): Loss-of-function variants: 19 observed, 35.99 expected, observed/expected ratio (o/e) 0.53, 90% interval 0.37 to 0.77. The upper end of that interval is the gene's LOEUF score, 0.77, which puts it in group 3 of 6, group 1 being the genes least tolerant of losing a copy. Missense variants: 434 observed, 540.88 expected, observed/expected ratio (o/e) 0.8, 90% interval 0.74 to 0.87. Synonymous variants: 180 observed, 199.68 expected, observed/expected ratio (o/e) 0.9, 90% interval 0.8 to 1.02.
Homologues: Orthologues: chimpanzee FGL2 (99% identical), macaque FGL2 (99% identical), pig FGL2 (89% identical), rabbit FGL2 (88% identical), dog FGL2 (83% identical), mouse Fgl2 (77% identical), rat Fgl2 (77% identical), guinea pig FGL2 (65% identical), tropical clawed frog fgl2 (60% identical), zebrafish fgl2a (54% identical), zebrafish fgl2b (46% identical). Paralogues in human: TNXB (30% identical), TNC (30% identical), TNR (28% identical), TNN (28% identical), ANGPT1 (27% identical), ANGPT2 (27% identical), FGB (27% identical), FGL1 (25% identical), FIBCD1 (25% identical), ANGPTL1 (24% identical), ANGPT4 (24% identical), FN1 (24% identical), and 13 more.
Diseases named in the same sentence as FGL2 in open-access papers:
FGL2 is named in the same sentence as 130 diseases in open-access papers, as found by Europe PMC text mining. Sharing a sentence is not in itself a finding about the gene and the disease. The quoted sentences say what the papers report.
glioma (33 papers, 2015 to 2025). A benign or malignant brain and spinal cord tumor that arises from glial cells (astrocytes, oligodendrocytes, ependymal cells). "In conclusion, our current study indicated that overexpression of FCGR3A and FGL2 is associated with poor prognosis in primary and recurrent glioma patients, especially in LGG." (PMID 39629005, 2024). "The tumors treated with anti-FGL2 antibody were also found to have lower CD44 expression and higher Olig2 expression than the control group, indirectly demonstrating that high expression of FGL2 is associated with the mesenchymal subtype of glioma." (PMID 36313679, 2022). "At the same time, FGL2 is implicated in the malignant progression of tumors in hepatocellular carcinoma, central nervous system tumors, breast cancer, ovarian cancer and so on." (PMID 36313679, 2022). "Our previous data show that FGL2 is highly expressed in glioma and is associated with poor prognosis in glioma patients." (PMID 30683885, 2019). "The increased expression of FCGR3A and FGL2 is associated with various clinical features in glioma." (PMID 39629005, 2024). "In glioma patients, fibrinogen-like protein 2 (FGL2) produced by cancer cells interacts with the GM-SCF signaling, which influences differentiation of CD103+cDC1s and limits CD8+ T cells immune response." (PMID 40136652, 2025). "In experiments targeting FGL2 (an immune‐suppressive regulator) for the treatment of gliomas, blocking FGL2 on T cells increased CXCR3 expression on CD8+ TRM, promoted their proliferation, and enhanced granzyme B secretion." (PMID 41388658, 2025). "Upregulation of Fgl2 by tumor and stromal cells (e.g., hepatocellular carcinoma and glioma) have been correlated with poor patient survival." (PMID 40125553, 2025). "In mouse models of glioma and hepatocellular carcinoma, Fgl2 from the tumor conferred cancer cells with stem-like qualities, inhibited CD103+ dendritic cell maturation, and skewed myeloid cells to a protumorigenic state." (PMID 40125553, 2025). "Our results show that in mRNA level, FGL2 is only expressed in CD16+ myeloid cells in gliomas, a subpopulation mainly responsible for phagocytosis, antigen processing, presentation, and activation of T-cells." (PMID 39629005, 2024). "MRNA expressions of FCGR3A and FGL2 were significantly upregulated in Low-grade gliomas and glioblastomas respectively compared to normal brain tissue, and there are few mutations in either 2 genes." (PMID 39629005, 2024). "In glioma, tumor cells secrete fibrinogen-like protein 2 (FGL2), which inhibits the development of granulocyte-macrophage colony-stimulating factor (GM-CSF)-induced CD103+ DCs." (PMID 39452154, 2024). "It shows that the high expression of FCGR3A and FGL2 in glioma is induced by tumor cells or immune cells infiltrated into the brain." (PMID 39629005, 2024). "Despite the growing interest in FCGR3A and FGL2 effect in glioma, their clinicopathological significance and prognostic value have received less attention." (PMID 39629005, 2024). "A study on gliomas revealed that targeting FGL2 depletion activates anti-tumor activity of CD8+T cells by facilitating the differentiation of CD103+ DCs." (PMID 38816776, 2024). "FGL2 has been shown to function as a promoter of glioblastoma progression and of stem-like transition of glioma cells by augmenting immunosuppression." (PMID 39629005, 2024). "Cox regression analysis further confirmed that elevated expression of FCGR3A and FGL2 were independent prognostic factors for shorter overall survival in glioma patients." (PMID 39629005, 2024). "Overexpression of FCGR3A and FGL2 is regarded as independent prognostic factors for shorter OS of glioma patients through Cox regression analysis." (PMID 39629005, 2024). "We previously showed that glioma samples were positive for FGL2 by using homemade antibody, indicating that detecting antibody is important for FGL2 staining." (PMID 39629005, 2024).
glioma (continued). "FCGR3A is significantly positively correlated with FGL2 expression in all tumor types (R=0.43), while the correlation between FCGR3A and FGL2 is more prominent in glioma samples (R=0.79)." (PMID 39629005, 2024). "This similar mechanism has also been observed in glioma, where FGL2 interacts with thrombin and tissue factors to induce a hypercoagulable state within the tumor, ultimately promoting tumor angiogenesis and metastasis." (PMID 38816776, 2024). "Studies have shown that glioma orthotopic planting model successfully established in mice with systemic knockout of FGL2, but FGL2-KO tumor cells cannot be established in immunocompetent mice." (PMID 39629005, 2024). "This study aims to evaluate the prognostic value of FGL2 transcription expression in glioma, determine the cell types that express FGL2 in human glioma, and to explore how the type of cells affect the generation and progression of glioma." (PMID 39629005, 2024). "Given that the expression levels of FCGR3A and FGL2 exhibit similar trends across different subtypes of gliomas and the anatomical localization is the same in tumor, we propose that FCGR3A and FGL2 co express on a type of cell within gliomas." (PMID 39629005, 2024). "The results of Cox regression analysis further demonstrate the independent prognostic significance of FCGR3A and FGL2 in glioma." (PMID 39629005, 2024). "The mass spectrometry results show that the abundance of FCGR3A and FGL2 proteins were also upregulated in glioma tissues in the CPTAC database." (PMID 39629005, 2024). "FCGR3A and FGL2 transcriptional expressions are found significantly higher in glioma compared with normal brain." (PMID 39629005, 2024). "Our studies are corroborated by a recent report which showed that blocking Fgl2 in glioma results in a preservation of FcγRIIB+ CD8+ T cells in mice." (PMID 38902261, 2024). "This work extends the work of other groups that have shown that Fgl2 has a protumor role in the context of glioma and hepatocellular carcinoma." (PMID 38902261, 2024). "Patients with FGL2 overexpression have an adverse prognosis in human glioma, clear cell carcinoma, and other cancers." (PMID 39575432, 2024). "Given that the expression levels of FCGR3A and FGL2 exhibit similar trends across different subtypes of gliomas and the anatomical localization is the same in tumor, we propose that FCGR3A and FGL2 co express in gliomas." (PMID 39629005, 2024). "We previously found that FGL2 produced by glioma cells acts on the CD16 receptor of macrophages in the microenvironment through paracrine signaling." (PMID 39629005, 2024). "To test the efficacy of T-αFGL2 therapy in vivo, we first validated expression of FGL2 in mouse glioma tissue." (PMID 36759517, 2023). "The authors concluded that FGL2 serves as an onco-immune target and that its overexpression in glioma cells affects the differentiation of DCs." (PMID 38275375, 2023). "Here, to improve the efficacy of FGL2 blockade for glioma treatment, we generate T cells armed with an FGL2-blocking single-chain variable fragment (scFv)." (PMID 36759517, 2023). "FGL2 was previously shown by our group to be involved in the malignant transformation of low- to high-grade gliomas and is expressed in other cancers, such as HCC, prostate, B cell lymphoma, colorectal, and lung cancers." (PMID 37115694, 2023). "Brain tissue samples from DBT glioma-bearing mice (an immunocompetent syngeneic mouse glioma model) were cryosectioned and stained with FGL2 mAb-clone #4." (PMID 36759517, 2023). "FGL2, IL10, TGFB1, and VEGFA were secreted immunosuppressive molecules in glioma and were consistently upregulated in high-risk group from all four datasets." (PMID 37864127, 2023). "Expression of FGL2 by glioma cells leads to the suppression of the dendritic cell marker CD103 by blocking granulocyte macrophage colony-stimulating factor (GM-CSF), which in turn leads to defective differentiation of DCs." (PMID 38275375, 2023).
glioma (continued). "Overexpression of FGL2 in a mouse glioma model was observed to increase CD4+FoxP3tregs cells and induced macrophages toward M2 phenotype shift." (PMID 36313679, 2022). "FGL2 is widely expressed in gliomas and also plays an essential immunosuppressive role, thereby promoting tumor immune escape and malignant progression." (PMID 36313679, 2022). "In-depth understanding and elucidation of the transcriptional and signaling mechanisms of FGL2 in different cell types of gliomas are essential for developing new specific targeted drugs." (PMID 36313679, 2022). "Although the origin of FGL2 in glioma is not fully understood, it has been shown to be expressed mainly in immune cells such as endothelial cells, macrophages, NK cells, T cells and tumor cells." (PMID 36313679, 2022). "Recent studies have shown that FGL2 can contribute to the growth of gliomas by inducing multiple immune mechanisms." (PMID 36313679, 2022). "In gliomas, Fibrinogen-like protein 2 (FGL2) secreted by glioma cells recruits macrophages to the TME and induces CXCL7." (PMID 35837284, 2022). "FGL2 upregulation in glioma has been validated as an immune suppressor and is involved in malignant progression." (PMID 36119086, 2022). "were the first to identify the strong expression of FGL2 in gliomas and conducted experiments to prove it." (PMID 36313679, 2022). "FGL2 is overexpressed in glioma, and its expression level is negatively correlated with the prognosis of patients with glioma." (PMID 35602471, 2022). "In GBM, targeting expression of FGL2 in vivo can strengthen the immune function and improve the therapeutic outcome of glioma patients." (PMID 33867830, 2021). "At the same time, FGL2 promotes glioma progression by inhibiting CD103+ dendritic cell differentiation." (PMID 33511267, 2020). "Increased FGL2 expression has been identified in several human tumors, including glioma, lymphoma, lung cancer and liver cancer." (PMID 33323552, 2020). "FGL2 enhances the immunosuppressive effect of glioma by increasing the expression level of PD1, increasing the M2 phenotype macrophages, and increasing the number of MDSCs and Tregs." (PMID 33511267, 2020). "FGL2 has been identified as an important immune-suppressive modulator and as a potential immunotherapeutic target for treating gliomas." (PMID 32596316, 2020). "Previous studies report reductions in tumor growth following Fgl2 knockout in glioma and lung cancer models." (PMID 31409352, 2019). "Flow cytometric analysis of FGL2 expression showed 1.7–11.5% FGL2 positive-staining glioma cells among disaggregated GSC neurospheres." (PMID 30683885, 2019). "In glioma and lung tumor models, levels of MDSCs and M2 macrophages decreased in tumors in Fgl2-knockout groups, suggesting an sFGL2-mediated mechanism promoting tumor growth through increases in these two subsets." (PMID 31409352, 2019). "Single-cell suspensions derived from fresh ex vivo GBM specimens demonstrated that FGL2 expression occurred primarily in the glioma subpopulation that expressed glia-specific marker GFAP (43.3 ± 14.3% of GFAP+ cells)." (PMID 30683885, 2019). "Here we show that fibrinogen-like protein 2 (FGL2) is highly expressed in glioma stem cells and primary glioblastoma (GBM) cells." (PMID 30683885, 2019). "In conclusion, our findings suggest that FCGR3A and FGL2 could serve as promising prognostic biomarkers and potential therapeutic targets for glioma patients." (PMID 39629005, 2024). "First, the transcription expression level of FCGR3A/FGL2 among glioma patients were investigated." (PMID 39629005, 2024). "By searching the protein staining results of CD16 and FGL2 in the HPA database, it shows that normal brain tissue (cortex) does not contain CD16 or FGL2 positive cells, but the number of CD16+cells increase significantly in glioma samples, and FGL2 doesn’t show positive staining." (PMID 39629005, 2024).
glioma (continued). "This study could provide deeper insights into the prognostic value of FCGR3A and FGL2 expression in glioma, potentially leading to improved patient stratification and treatment strategies." (PMID 39629005, 2024). "We have shown through a series of studies of preclinical glioma that FGL2 increases the expression of PD-1 and the frequency of tumor-supportive macrophages and Tregs, suppresses the development of CD103+ DCs, and blocks the recruitment of tumor-specific, brain-resident memory T cells." (PMID 37115694, 2023). "Both glioma cells and surrounding stroma positively stained for FGL2." (PMID 36759517, 2023). "A subsequent study by the same authors has shown that glioma-derived FGL2 induces secretion of PPBP (CXCL7) by a subset of TAMs following activation of FGL2/CD16/PI3K/Akt/HIF1α signalling, which promotes the expression of stem-like properties in glioma cells (Molecular event 23)." (PMID 36555253, 2022). "We summarize the molecular mechanisms by which FGL2 may be expressed in various cell types and explore the potential prognostic value and immunotherapeutic targeting of FGL2 in gliomas." (PMID 36313679, 2022). "As a molecule with such a role, the development of inhibitors of FGL2 may help reverse immunosuppression in the tumor microenvironment and may play an essential role in targeting glioma-mediated immunosuppressive therapy." (PMID 36313679, 2022). "FGL2 promotes glioma progression by inhibiting CD103+ dendritic cell differentiation." (PMID 36313679, 2022). "FGL2 was shown to be upregulated in glioblastoma and correlates with glioma grade and tumor growth." (PMID 31225500, 2019). "Recent studies showed that FGL2 plays a role in MDSC glioma accumulation." (PMID 31225500, 2019). "Moreover, Gene co-expression network analysis enlightens us that abnormal adaptive immune activation and specific CD16-related Immune paralysis blocking by targeting FCGR3A and FGL2 might be a new idea for treating glioma." (PMID 39629005, 2024). "However, the role of FGL2 in gliomas and the therapeutic potential to target this protein in cancer patients remains unclear." (PMID 36313679, 2022). "FGL2 can modulate immune reactions and may be a potential immunotherapeutic target in glioma." (PMID 35127943, 2022). "Therefore, the development of FGL2 inhibitors may play an important role in the immunotherapy of gliomas." (PMID 36313679, 2022). "verified that FGL2 might promote glioma growth in murine models by inhibiting the infiltration of immunosuppressive cells in the tumor microenvironment and that neutralization of FGL2 protein using anti-FGL2 antibody prolonged the survival time of mic." (PMID 36313679, 2022). "Among the three transcriptional subtypes of glioma, the mesenchymal subtype tumors have the highest expression level of FCGR3A and FGL2 as compared with classical or proneural subtypes." (PMID 39629005, 2024). "TGFB1, VEGFA, ARG1, FGL2 and IL10 are secreted immunosuppressive factors in glioma, while CD95L and CD70 are glioma cell‐surface immunosuppressive factors." (PMID 33611848, 2021). "Compared with low-grade gliomas, GBM tumors had remarkably higher mRNA and protein levels of FGL2, and the elevated FGL2 levels were shown to be related to a lower overall survival rate in GBM patients." (PMID 27732962, 2017). "By transferring delayed brain tumor glioma cells into mice, the authors constructed GBM murine models and found that anti-FGL2 antibody treatment led to significantly prolonged survival time." (PMID 27732962, 2017). "It indicates that FGL2+CD16+monocytes exist in the peripheral blood under physiological conditions and are recruited through intra-tumoral blood vessels during the occurrence of gliomas." (PMID 39629005, 2024).
glioma (continued). "Regarding the investigation of the specific role of DCs in gliomas, an important breakthrough seems to be the recent finding of the role of fibrinogen-like protein 2 (FGL2) expressed in immune cells and in glioma cells, and this expression correlates with a worse clinical outcome." (PMID 38275375, 2023). "The glioma microenvironment secretes a variety of immunosuppressive factors, such as TGF-β2, prostaglandin E2 (PGE2), IL-1, IL-10 and fibrinogen-like protein 2 (FGL2)." (PMID 37686020, 2023). "However, the role of FGL2 in TME and the therapeutic potential of targeting this cytokine in gliomas is unclear." (PMID 36313679, 2022). "Although the cellular origin of FGL2 in gliomas has not been determined, it has been shown that FGL2 is higher expressed in glioblastoma and glioblastoma stem cells (GSCs) compared to fibroblast cells." (PMID 36313679, 2022). "However, the relationship between FGL2, TAMs and gliomas cells has not been sufficiently studied, and more experiments are needed to verify the relationship in the future." (PMID 36313679, 2022). "Nevertheless, there are no relevant literature reports on whether FGL2 has an effect on tumor angiogenesis in glioma, and more experimental validation may be needed at a later stage." (PMID 36313679, 2022). "FGL2 knockout in glioma cells did not affect the proliferation of tumour cells in immunocompromised mice but completely impaired glioblastoma progression in immune‐competent mice, suggesting that FGL2 has an important role in regulation of the immune environment in glioblastoma." (PMID 35029030, 2022). "Notably, this was not secondary to FGL2’s impact on the cell growth rate, because both FGL2KO and Ctrl glioma cells proliferated equally in vitro." (PMID 30683885, 2019).